SMAD7 (SMAD family member 7)
Diseases named in the same sentence as SMAD7 in open-access papers (continued):
Sharing a sentence is not in itself a finding about the gene and the disease.
liver fibrosis (continued). "Results of the correlation analysis between TGF-β1, Smad7 and liver fibrosis markers in murine AE (from the histo-immunochemistry analysis)." (PMID 23405141, 2013). "Results of the correlation analysis between TGF-β1, Smad7 and liver fibrosis markers in human AE (from the histo-immunochemistry analysis)." (PMID 23405141, 2013). "For example, adenovirus-mediated overexpression of Smad7 in the liver potently blunted bile duct ligation-induced liver fibrosis and efficiently inhibited intracellular TGF-β signalling." (PMID 22978413, 2012). "The mechanism of AA-induced upregulation of hepatic Smad7 to inhibit CCl4-induced liver fibrosis was further investigated in vitro by knocking down Smad7 in HSC-T6 cells." (PMID 22363627, 2012). "Our in vivo results showed that curcumin administration to rats with CCl4-induced liver fibrosis markedly induced Smad7 mRNA and protein expression as compared with rats treated with CCl4 alone." (PMID 22978413, 2012). "In the mice, either overexpression or down-regulation of Smad7 in the liver has been used to investigate the effect of Smad7 on liver fibrosis." (PMID 22204639, 2011). "Our results are also consistent with the report demonstrating that partial loss of Smad7 function can increase EMT in the liver and accelerates CCl4-induced liver fibrosis." (PMID 21386907, 2011). "Notably, recent mechanistic studies indicate that hydronidone ameliorate liver fibrosis by inhibiting HSCs activation through a mechanism involving Smad7‐mediated degradation of TGF‐β receptor I (TGFβRI)." (PMID 41487942, 2026). "SMAD7 serves as a competitive inhibitor of TGFβR, suppressing this pathway activation and fibrosis progression, making it an important negative regulator of liver fibrosis." (PMID 40651612, 2025). "Additionally, circ-MTO1, derived from the MTO1 gene, has been found to suppress liver fibrosis by regulating the miR-17-5p/Smad7 axis." (PMID 40248098, 2025). "Similarly, BCAAs, composed of leucine, isoleucine, and valine, regulated the expression of TGF-β1, Smad-3, α-SMA, and Smad-7 in CCl4-induced liver fibrosis rats." (PMID 38111317, 2024). "GPR81 might be a detrimental factor that promotes the development of liver fibrosis by regulating CREB/Smad7 pathway." (PMID 38982366, 2024). "Whether Smad7 methylation plays a vital role in the effects of Rg1 on liver fibrosis remains unclear." (PMID 37397418, 2023). "Specifically, CircPSD3 alleviates the formation of liver fibrosis via miR-92b-3p/Smad7 axis, which suggests that CircPSD3 may be a potential biomarker for HF." (PMID 37371520, 2023). "Furthermore, TPLR inhibited TGF-β/Smad pathway ameliorating hepatic fibrosis though downregulation the expression of Smad2/3, Smad4, and upregulation the expression of Smad7 in vivo and in vitro." (PMID 36829153, 2023). "Next, we examined whether Smad7 promoter demethylation is involved in the Rg1-mediated inhibition of liver fibrosis." (PMID 37397418, 2023). "study, which found that miR-17 promotes HSC activation by reducing smad-7, implying that it may be useful as a new therapeutic target for liver fibrosis." (PMID 34894966, 2022). "Moreover, previous reports have suggested that downregulation of miRNA-21 in HSCs alleviates liver fibrosis through overexpression of Smad7, and miRNA-454 directly targets Smad4 to inhibit the activation of HSCs." (PMID 36474240, 2022). "Moreover, in a model of liver fibrosis, hepatocyte-specific Smad7 expression reduced liver fibrogenesis." (PMID 34905511, 2022). "We also analyzed liver fibrosis after adenoviral overexpression of PROM1 or SMAD7." (PMID 36038590, 2022). "Downregulation of miRNA-21 in HSCs attenuated liver fibrosis through overexpression of Smad7." (PMID 36474240, 2022). "Furthermore, ADSCs transplantation regulated the activation levels of the TGF-β receptors and Smad7 signaling pathway in the livers of E. multilocularis infected mice, suggesting that ADSCs rescue liver fibrosis by up-regulating Smad7 signaling." (PMID 35100287, 2022).
liver fibrosis (continued). "High Smad7 expression is associated with several inflammatory conditions, including CMV colitis and necrotizing enterocolitis, but, when overexpressed, can also attenuate liver fibrosis." (PMID 34769006, 2021). "Furthermore, miR-497 inhibitor delivered by highly-hepatotropic (rAAV8) inhibited TGF-β/smads signaling pathway by targeting at Smad7 to ameliorate CCL4-induced liver fibrosis." (PMID 34521449, 2021). "To further confirm the in vitro findings, we established a liver fibrosis mouse model by the injection of CCl4 for 6 weeks to check whether miR-497 can regulate Smad7 to promote liver fibrosis in vivo." (PMID 34521449, 2021). "Smad7 has been shown to inhibit the activation of HSCs and prevent liver fibrosis." (PMID 34323416, 2021). "Here, we analysed whether Smad7 function in LysM-expressing myeloid cells influenced the induction of liver fibrosis in the model of chronic CCl4 application." (PMID 34769006, 2021). "Further study showed that treatment of miR-497 inhibitor depressed the activation of HSCs and liver fibrosis both in vivo and in vitro by targeting Smad7, indicating that anti-miR-497 might be a promising therapeutic strategy for liver fibrosis." (PMID 34521449, 2021). "To investigate the underlying mechanism of the effect of hFSSC secretome on liver fibrosis, we performed the Western blot and RT-qPCR to analyze the expression of TGF-β1, Smad2, Smad3, Smad7, and Collagen I in HSCs, as it is one of the major effector cells in liver fibrosis." (PMID 32883340, 2020). "To test our hypothesis, we observed the effect of three different doses of SSTF on protein expression and mRNA levels of TGF-β1 and Smad7 using a rat model of schistosomiasis-induced liver fibrosis." (PMID 33293986, 2020). "Treatment with Smad7-MSCs significantly reduced the level of collagenases, suggesting that the cell therapy with Smad7-MSCs is effective in the prevention of liver fibrosis." (PMID 32928296, 2020). "Activation of TGF-β1/Smad signalling accelerates liver inflammation and fibrosis; we therefore hypothesized that MSCs overexpressing the Smad7 gene might be a new cell therapy approach for treating liver fibrosis via the inhibition of TGF-β1/Smad signalling." (PMID 32928296, 2020). "Taken together, we demonstrate that circMTO1 inhibits liver fibrosis via regulation of miR‐17‐5p and Smad7, and serum circMTO1 may be a novel promising biomarker of liver fibrosis." (PMID 31148365, 2019). "In the miR-29a transgenic mice, Smad7 maintained an abundance that was more than twice as great (miR-29a-sham vs. WT-sham, p < 0.001), thus providing evidence of its protection ability against liver fibrosis." (PMID 26938532, 2016). "We recently found that AA exerts its anti-fibrotic effects on liver fibrosis by inducing Smad7." (PMID 26474462, 2015). "The aim of our study was to determine whether Smad7 expression correlates with the gene expression of TGF-β, Col I, Col III, Col IV, and PAI-1 in patients with liver fibrosis caused by BDI." (PMID 19878580, 2009). "Taken together, the present study found that liver fibrosis is associated with the upregulation of GPR81, which might be a detrimental event that promotes the development of liver fibrosis via suppression of CREB/Smad7 pathway." (PMID 38982366, 2024). "Thus, miR-21 and miR-96 could activate collagen generation and stimulate liver fibrosis by targeting SMAD7 and trigger the pro-fibrotic function of the TGF-β1/SMAD signaling pathway." (PMID 35756064, 2022). "In addition, the results of the current study indicated that the hepatic level of smad-7 was significantly reduced by 58.0%, whereas hepatic levels of smad-3 and collagen a1 were raised by 4.5- and 6.3-fold, respectively in the liver fibrosis group compared to the control group." (PMID 34894966, 2022).
liver fibrosis (continued). "Smad7 cannot be induced by the pSmad3L pathway in chronic liver injury, leading to constitutive fibrogenesis in MFBs; thus, the low expression of Smad7 in liver fibrosis may promote liver fibrosis progression." (PMID 28929107, 2017). "Therefore, in this research we investigated the therapeutic effect and mechanisms of CGA on anti-fibrosis by interacting with the miR-21-regulated TGF-β1/Smad7 signaling pathway in CCl4-induced liver fibrosis rat model and TGF-β1-stimulated human HSC line LX-2." (PMID 29311932, 2017). "Therefore, interfering with the miR-21-regulated TGF-β1/Smad7 signaling pathway may be another effective method to block the development of liver fibrosis." (PMID 29311932, 2017). "Chlorogenic acid inhibits the expression of miR-21, α-SMA, and TGF-β, while increasing the protein expression of Smad7 and matrix metalloproteinase-9 (MMP-9), thereby alleviating liver fibrosis." (PMID 41154556, 2025). "HCV infection upregulates miRNA expression, downregulates Smad7 and HGF, have a role in development of liver fibrosis." (PMID 39185567, 2025). "In the present study, the inhibitory effects of DHBA/GPR81 on the anti-fibrotic CREB/Smad7 pathway have been verified in TGF-β1-activated LX-2 cells and CCl4-insulted mice, which might represent an important mechanism underlying the detrimental activity of GPR81 in liver fibrosis." (PMID 38982366, 2024). "This CD133–Smad7 interaction inhibited the SMURF2-induced ubiquitination of Smad7 and increased its half-life, resulting in a reduction in the TGF-β-induced liver fibrosis and apoptosis rates of hepatocytes." (PMID 38532366, 2024). "Through regulating IL-13/miR-21/Smad7 signaling interactions, CGA inhibited schistosomiasis-induced liver fibrosis." (PMID 36838754, 2023). "Smad7 is an interesting target for anti-SSLF therapy, and Smad7 overexpression in HSCs significantly relieves liver fibrosis." (PMID 36389166, 2022). "Coadministration of ADSCs and HGF on diabetic mice with liver fibrosis enhanced antifibrotic effects confirmed by the downregulation of Col I, α-SMA, TGF-β1, and Smad2, while Smad7 was upregulated." (PMID 36359733, 2022). "The activation of TGF-β signaling decreases the bone morphogenetic protein and activin membrane-bound inhibitor (BAMBI), SMAD7, and increases the SMAD2/3/4 proteins, resulting in the excessive production of ECM and the progression of liver fibrosis." (PMID 35051234, 2022). "The affected tissues had increased mRNA levels of miR-21 and CTGF with a decrease in the level of Smad7 and CGA, which prevented these changes and liver fibrosis in an animal model of liver fibrosis induced by Schistosoma japonicum cercaria infection." (PMID 35744941, 2022). "All these data suggested that GZFL was able to ameliorate liver fibrosis in vitro and in vivo by modulating the crosstalk between TGF-β1/Smad2/3 and IFN-γ/STAT1/Smad7 signaling pathway via CUGBP1." (PMID 35387552, 2022). "Low SMAD7/high YAP1 levels were confirmed in both HCC and rat models with advanced liver fibrosis and cirrhosis." (PMID 33763375, 2021). "Liver biopsies of HCV-related liver fibrosis samples indicate upregulation of miR-21, and this miRNA enhances TGF-β signaling by targeting SMAD7, a negative regulator of TGF-β, and consequently induces fibrogenesis." (PMID 34360904, 2021). "miR-21 induces NASH via the STAT3 signaling pathway and induces liver fibrosis via HSC activation and collagen deposition via the TGF-β/Smad3/Smad7 signaling pathway." (PMID 34360904, 2021). "Recently, it was reported that miR-96, like miR-21, promotes schistosomiasis-related hepatic fibrosis by activating the SMAD signaling pathway, and increases collagen expression by targeting SMAD7." (PMID 33171811, 2020). "To explore the mechanism of SSTF's effect on liver fibrosis, we measured TGF-β1 and Smad7 protein expression." (PMID 33293986, 2020).
liver fibrosis (continued). "Our study shows that SSTF treatment can reduce schistosomiasis-induced liver fibrosis by downregulating TGF-β1 and upregulating the Smad7 expression in liver tissue, thus preventing TGF-β1 from activating HSCs and reducing the degree of hepatic fibrosis." (PMID 33293986, 2020). "Smad7 is a negative regulator, and its overexpression can block HSC activation and hepatic fibrosis progression and even reverse hepatic fibrosis." (PMID 33293986, 2020). "Previous studies have shown that some Chinese medicines can reverse hepatic fibrosis by reducing TGF-β1 and increasing Smad7." (PMID 33293986, 2020). "Long intervening noncoding RNA-p21 (lincRNA-p21) is upregulated in CCl4-induced liver fibrosis and acts as endogenous competitive inhibitor of miR-30, which inhibits TGF-β signaling through targeting KLF11 and by increasing SMAD7 expression." (PMID 31718044, 2019). "LIG prevents and alleviates the development of liver fibrosis by downregulating TGFβ1, TβRII, CCN2, and Smad2/3, and type I collagen while upregulating Smad7 and inhibits proliferation of hepatic stellate cells." (PMID 31886227, 2019). "HIC5 knockdown attenuated liver fibrosis in CCl4 and BDL animal models through upregulation of SMAD7 expression." (PMID 31718044, 2019). "Suppression of Smad7 by DNA methyltransferase 1 promoted the phosphorylation of Smad2 and Smad3 that had been induced by HSC activation, or liver fibrosis in general." (PMID 25435153, 2015). "In contrast, Smad7 is protective since deletion of Smad7 promotes, but overexpression of Smad7 protects against HSC activation and hepatic fibrosis in vitro and in vivo." (PMID 22363627, 2012). "For instance, asiatic acid has been shown to attenuate CCl4‐induced liver fibrosis in rats and suppress TGF‐β1‐stimulated activation of HSCs in vitro by upregulating Smad7, thereby blocking Smad2/3 phosphorylation, reducing α‐SMA and collagen matrix expression." (PMID 41487942, 2026). "Glycyrrhizic acid, an active metabolite derived from Glycyrrhiza uralensis Fisch (Gancao), can ameliorate liver fibrosis and inhibit hepatic stellate cell activation by enhancing the CUGBP1-mediated IFN-γ/STAT1/Smad7 pathways, indicating its potential as a preventive agent for liver fibrosis." (PMID 39301567, 2024). "Smad2/Smad3, a downstream factor of Smad signaling, is considered a key regulator of TGF-β signaling in tissue fibrogenesis, and more importantly, Smad7 is a potential major transcriptional repressor of HSC activation and liver fibrosis in vitro and in vivo, regulating Smad2/Smad3 phosphorylation." (PMID 37056286, 2023). "Interestingly, Smad7, a negative regulator of the transforming growth factor β (TGF-β) pathway, is often methylated during liver fibrosis." (PMID 37397418, 2023). "Consequently, CircMTO1 inhibited HSC activation through the miR-17-5p/Smad7 axis or miR-181b-5p-mediated PTEN expression, ultimately slowing down liver fibrosis." (PMID 37371520, 2023). "Perhaps through the regulation of the miR-21-regulated TGF-β1/Smad7 signaling, CGA suppressed the CCl4-induced liver fibrosis, which suggested that CGA might be a new anti-fibrosis agent to improve liver fibrosis." (PMID 36838754, 2023). "In the context of liver fibrosis, Smad7 acts as a negative feedback regulator, inhibiting the TGF-β1/Smad signaling by preventing the binding of activated TβRI to Smad2/Smad3." (PMID 36474240, 2022). "BDL-induced liver fibrosis was aggravated with increased phosphorylation of SMAD2/3 and decreased levels of SMAD7 by global or liver-specific Prom1 deficiency but not by cholangiocyte-specific Prom1 deficiency." (PMID 36038590, 2022). "Up-regulated TGF-β1 and down-regulated Smad7 in E. multilocularis infected mice were partially abolished by ADSCs transplantation, indicating that ADSCs regulate the TGF-β/Smad7 signaling pathway to ameliorate liver fibrosis." (PMID 35100287, 2022).
liver fibrosis (continued). "Collectively, GZFL could reduce CCl4-induced liver fibrosis in vivo by inhibiting TGF-β1/Smad2/3, CUGBP1 signaling and activating IFN-γ/STAT1/Smad7 signaling." (PMID 35387552, 2022). "The expression of TGF-β1, Smad2/3, p-Smad2/3, and Smad4 sharply increased as liver fibrosis progressed and peaked at 7 or 9 wpi, while the negative regulator Smad7 dramatically decreased at 9 wpi." (PMID 36474240, 2022). "GZFL could inhibit acetaldehyde‐induced cellular fibrosis and alleviate CCL4‐induced liver fibrosis by inhibiting TGF-β1/Smad2/3, CUGBP1 signaling and activating IFN-γ/STAT1/Smad7 signaling." (PMID 35387552, 2022). "Our data suggest that miR-497 promotes liver fibrogenesis by targeting Smad7 to modulate the TGF-β/Smad signaling pathway both in vivo and in vitro, which suggests that anti-miR-497 treatment represents a promising therapeutic strategy in liver fibrosis." (PMID 34521449, 2021). "However, the group treated with Smad7-MSCs for 21 days significantly reduced histopathological fibrosis scores, suggesting that Smad7-MSC-base gene therapy can reduce liver fibrosis." (PMID 32928296, 2020). "However, this increase in TGFβ and Smad2/3 expression is offset by overexpression of Smad7, resulting in attenuation of TAA-induced liver fibrosis." (PMID 30509307, 2018). "SMAD7 protein is known as the inhibitory SMAD (I-SMAD) or the protective SMAD that switches off signaling of TGF-β1/SMAD, as well as nuclear factor kappa (NF-κB) in liver fibrosis." (PMID 30254303, 2018). "In opposite to Smad2/3, Smad7 serves as an inhibitory Smad that could block the activation of TGF-β1 signals via inhibition of Smad2/3, playing a protective role in liver fibrosis." (PMID 29743985, 2018). "Chlorogenic acid exerts the ability to suppress liver fibrosis through regulation of the miR-21-regulated TGF-β1/Smad7 signaling pathway in vivo and in vitro, which suggests that CGA may be an attractive anti-liver fibrosis agent." (PMID 29311932, 2017). "Overexpression of Smad7 in mouse liver could attenuate TGF-β signaling and TGF-β-induced EMT, while improve CCl4-provoked liver fibrosis." (PMID 21386907, 2011). "Overexpression of Smad7 in mouse liver could attenuate TGF-β signaling and improve carbon tetrachloride (CCl4)-provoked liver fibrosis." (PMID 21386907, 2011). "The aim of the study was to determine whether Smad7 mRNA expression correlates with the gene expression of TGF-β, Col I, Col III, Col IV, or PAI-1 in liver fibrosis secondary to bile duct injury (BDI)." (PMID 19878580, 2009). "Additionally, TGFβ has been known to increase ROS generation, which plays a crucial role in stimulating liver fibrosis As a negative-feedback regulator, Smad7 interferes with the interaction between TGFβ type I receptor and Smad2." (PMID 37446633, 2023). "Moreover, SML protected against liver fibrosis in a dose-dependent manner as indicated by down-regulation of LPAR1, LPAR3, CTGF, TGF-β1/Smad3, and α-SMA expressions and a decrease in pSmad3 level, as well as an up-regulation of Smad7 expression." (PMID 35648193, 2022). "After extensive analysis of various parameters in chronically CCl4-treated LysM-Crepos x Smad7Δ/Δ mice and their LysM-Creneg Smad7fl/fl littermate controls, our results indicated that liver fibrosis development did not depend on the presence of Smad7 in LysM-expressing cells." (PMID 34769006, 2021). "In hepatocytes, the absence of Smad7 promotes liver fibrosis." (PMID 34769006, 2021). "The present study demonstrates that miR-497 promotes liver fibrogenesis by targeting Smad7 to promote TGF-β/Smad signaling pathway transduction both in vivo and in vitro, which provides a promising therapeutic strategy using anti-miR-497 against liver fibrosis." (PMID 34521449, 2021).